STAT3 (signal transducer and activator of transcription 3)
Diseases named in the same sentence as STAT3 in open-access papers (continued):
Sharing a sentence is not in itself a finding about the gene and the disease.
type 2 diabetes (54 papers, 2012 to 2026). "The genotype analysis results of rs9891119 of the STAT3 gene showed that the frequencies of A and C alleles of rs9891119 were 54.3% and 45.7% in the patients with type 2 diabetes, while 55.5% and 44.5% in the normal persons, respectively." (PMID 33833859, 2021). "However, the p-STAT3 inhibitor AG-490 protected against lung injury in a mouse model of type 2 diabetes-associated TB." (PMID 36882813, 2023). "In this study, we analyzed the SNP rs9891119 of the STAT3 gene and genetic susceptibility to type 2 diabetes involved in the leptin signaling pathway in Chinese Han population from Guangdong and explored whether there is a correlation between them." (PMID 33833859, 2021). "The aim of this study was to investigate the association between single nucleotide polymorphism (SNP) rs9891119 of the signal transducer and activator of the transcription 3 (STAT3) gene and genetic susceptibility to type 2 diabetes in Chinese Han population from the Guangdong province." (PMID 33833859, 2021). "Glucose fluctuations exacerbate myocardial fibrosis by triggering the CaMKII/Stat3 pathway in type 2 diabetes." (PMID 37891701, 2023). "In our study, we found that glucose fluctuations in type 2 diabetes exacerbated myocardial fibrosis via the CaMKII/Stat3 pathway." (PMID 37891701, 2023). "miR-125a-5p improved hepatic glucose and lipid metabolism disorders in patients with type 2 diabetes by targeting STAT3." (PMID 35955794, 2022). "Key mediators of the injury responses in islets transgenic for human IAPP or those from individuals with type 2 diabetes include STAT3, NF-κB, ESR1 and CTNNB1 by transcription factor analysis and COL3A1, NID1 and ZNF800 by gene regulatory network analysis." (PMID 34554282, 2022). "The SNPscanTM kit is used to investigate SNP rs9891119 of the STAT3 gene in the leptin signaling pathway between type 2 diabetes patients and normal persons in Chinese Han population from Guangdong." (PMID 33833859, 2021). "In our case-control study, the SNP rs9891119 was picked out from the STAT3 gene and the SNP genotyping was performed by using the SNPscanTM kit in 1092 patients with type 2 diabetes as cases and 1092 normal persons as controls." (PMID 33833859, 2021). "Moreover, metformin treatment of PCa patients with high Gleason grade and type 2 diabetes resulted in undetectable mTORC1 levels and upregulated STAT3 expression." (PMID 37573301, 2023). "Moreover, the ability of the CaMKII inhibitor KN-93 can counteract the fibrotic remodeling induced by GF in type 2 diabetes, underscoring the functional importance of the CaMKII/Stat3 interaction in myocardial fibrosis." (PMID 37891701, 2023). "Dioscin exerts many therapeutic effects on various diseases, such as regulating the inhibitory effect of miR-125a-5p on STAT3 signaling and reducing glucose and lipid metabolism disorders in Type 2 diabetes (T2DM) suggesting that it exhibits anti-T2DM activity." (PMID 35707715, 2022). "Interestingly, sEVs miRNA-mediated downregulation of STAT3 and impaired insulin signalling in skeletal muscles has been reported in type 2 diabetes." (PMID 34416903, 2021). "This study suggests that the polymorphism of rs9891119 of the STAT3 gene is not related to the susceptibility to type 2 diabetes in Chinese Han population from Guangdong." (PMID 33833859, 2021). "Our results showed that the alleles of A and C of rs9891119 of the STAT3 gene were 54.3 and 45.7% in patients with type 2 diabetes, while 55.5% and 44.5% in the normal persons, which have no statistical significance (P > 0.05)." (PMID 33833859, 2021). "In addition to the diabetes I model, reduced expression of cardiac STAT3 has been reported in a type II diabetes model, where a downregulation of STAT3 mRNA was observed in rats." (PMID 31709266, 2019). "TF network analysis uncovered four upstream hub transcriptional factors NF-κB, ESR1, STAT3 and CTNNB1 active in both type 2 diabetes and hIAPP islets." (PMID 34554282, 2022).
type 2 diabetes (continued). "Genes that increased EIIIA inclusion when deleted included Type II diabetes (KEGG), Stat3, and Stat5 signaling pathways, all of which are linked to insulin signaling responses." (PMID 34615942, 2021). "This systemic overabundance of proinflammatory cytokines in adipose tissue, including IL-6, activates STAT3 and subsequently AMPK leading to alterations in insulin signaling and eventually Type 2 diabetes." (PMID 32878032, 2020). "This led us to metformin, the first line medication for type 2 diabetes, which inhibits the ERK pathway as well as STAT3 signaling." (PMID 31805999, 2019). "Previous reports suggested that obese and type 2 diabetes patients have increased the level of TLR4 expression and involvement of NF-κB in human myotubes and p-STAT3 protein activation." (PMID 28706484, 2017). "For the AGC patients, high expression of STAT3, positive expression of pSTAT3, TNM stage, tumor size, and type 2- diabetes were all categorized as independent prognostic markers." (PMID 28061480, 2017). "Indeed, liraglutide, a first-line treatment for type 2 diabetes, has been reported to reduce inflammation and HFD-induced MASLD by modulating Kupffer cell M2 polarization through the STAT3 signaling pathway." (PMID 41415839, 2025). "Besides type I diabetes models, reduction of cardiac STAT3 expression was also described in a type II diabetes model, i.e., STAT3 mRNA was downregulated in non-obese Goto-Kakizaki rats." (PMID 30424579, 2018). "The genotype frequency and allele frequency were not significantly different between before and after adjusting (P > 0.05), suggesting that SNP rs9891119 of the STAT3 gene might not be directly related to type 2 diabetes in Chinese Han population from Guangdong." (PMID 33833859, 2021).
Cognitive impairment (52 papers, 2015 to 2026). Abnormal cognition is characterized by deficits in thinking, reasoning, or remembering. "Contradictorily, however, STAT3 overexpression restores synaptic loss and ameliorates cognitive deficits through modulation of the N-methyl-D-aspartate receptors (NMDARs) in an AD animal model, suggesting a beneficial role of STAT3 in AD." (PMID 39273571, 2024). "STAT3 hyperactivation has been linked to cognitive deficits in AD." (PMID 40801602, 2025). "The activation of JAK2/STAT3 may be useful in treating cognitive impairment associated with aging‐related disorders." (PMID 34262731, 2021). "STAT3 activation is dependent on the JAK2/STAT3 signaling pathway, and the activation of JAK2/STAT3 may be useful in treating cognitive impairment associated with aging‐related disorders." (PMID 34262731, 2021). "As cognitive disorders are associated with neuroinflammation and STAT3 plays an important role in the course of inflammation, we hypothesized that STAT3 and its downstream pathway may play an active role in the association between cognitive impairment and ligature-induced periodontitis." (PMID 33757547, 2021). "Thus, the activation of STAT3 cascades could be involved in the association between periodontitis and cognitive impairment." (PMID 33757547, 2021). "Conversely, in a mouse model of tauopathy expressing the human P301L mutant tau (P301L-hTau), overexpression of STAT3 was beneficial in rescuing P301L-hTau-induced synaptic and cognitive deficits." (PMID 39143450, 2025). "Accordingly, in this study, we investigated how Stat3-mediated Th17 pathogenicity contributes to the link between periodontitis and cognitive impairment." (PMID 40933993, 2025). "Stat3-mediated Th17 pathogenicity bridged the correlation between periodontitis and neuroinflammation related to cognitive impairment, offering novel perspectives for a therapeutic target for blocking the mouth-to-brain axis." (PMID 40933993, 2025). "The Th17/Treg ratio imbalance exacerbates cognitive impairment by modulating STAT3 activation in mice, potentially illustrating the immune regulatory effects of STAT3 through IL-6-mediated Th17/Treg levels." (PMID 40843259, 2025). "The conditional deleting of Stat3 in Th17 cells alleviated cognitive impairment in periodontitis mice, likely through the mitigation of Th17 pathogenicity and microglial inflammatory responses." (PMID 40933993, 2025). "This indicated that Stat3 was involved in how Th17 cells influence the correlation between periodontitis and cognitive impairment." (PMID 40933993, 2025). "Previous research has shown that ligature-induced periodontitis in rats causes inflammatory responses, cognitive impairments, and abnormal APP processing, with STAT3 pathway activation contributing to inflammation." (PMID 39822781, 2024). "A study found that STAT3 knockdown induced learning impairments and memory deficits, while overexpressing STAT3 rescued cognitive deficits." (PMID 38934552, 2024). "Previous studies have demonstrated that treatment with STAT3 inhibitors effectively improves cognitive impairment in animal models of AD." (PMID 39648181, 2024). "TIPE2 inhibits the activation of microglia by regulating the STAT3 and NF-κB pathways, improves the antioxidative and anti-inflammatory ability of hippocampal neurons, and inhibits apoptosis, thereby alleviating cognitive impairment." (PMID 37069964, 2023). "On the contrary, STAT3 is known to mediate astrogliosis and its inhibition was found to ameliorate cognitive impairments in AD mouse models and promote neurogenesis in neural stem cells." (PMID 37587513, 2023). "For instance, one study showed that an imbalance in Th17/Treg cells exacerbates cognitive impairment by activating the STAT3 pathway." (PMID 37808505, 2023). "NBP alleviates cognitive impairment following CCH by suppressing inflammation via modulation of STAT3/NF-κB signaling." (PMID 35615581, 2022).
Cognitive impairment (continued). "The suppression of the signal transducer and activator of transcription 3 (STAT3) enhanced cognitive impairment in APP/PS1 mice and reduced neuroinflammation." (PMID 36552875, 2022). "This study reveals a new mechanism underlying hTau accumulation induced cognitive deficits, and provides acetylated STAT1 or wild type STAT3 as a new therapy target for tauopathies." (PMID 33859760, 2021). "Two newest studies published in years 2019 and 2020 reported that STAT3 was a potential therapeutic target for cognitive impairment in AD58,59." (PMID 34131148, 2021). "Results from the present study suggest that CXCR5 contributes to cognitive impairment by enhancing p38MAPK/NF-κB/STAT3 signaling." (PMID 34711216, 2021). "For example, STAT3 modulates glial activation and Aβ deposition leading to cognitive impairment in AD transgenic models." (PMID 34720873, 2021). "Here, in order to explore the molecular mechanisms of STAT3 attenuating hTau-induced cognitive deficits, we detected NMDARs level while overexpressing STAT3." (PMID 33859760, 2021). "We also demonstrated that overexpressing STAT3 attenuated P301L-induced synaptic and cognitive deficits." (PMID 33361763, 2020). "Overexpressing STAT3 rescued P301L-hTau-induced synaptic and cognitive deficits by increasing NMDARs expression." (PMID 33361763, 2020). "Tau accumulation inhibits NMDARs expression via upregulation of STAT1 activity and downregulation of STAT3 activity, ultimately leading to synaptic dysfunction and cognitive deficits." (PMID 33361763, 2020). "We observed that the CCH process-induced cognitive impairment decreased CNTF/CNTFRα/JAK2/STAT3 signaling, and induced irreversible neuronal death in the hippocampus." (PMID 33519417, 2020). "To further certify the role of STAT3 in P301L-hTau-induced cognitive deficits, we co-injected AAV-P301L-hTau and AAV-STAT3 bilaterally into the hippocampal CA3 regions of 2-month-old C57 mice for 1 month." (PMID 33361763, 2020). "One recent study revealed that consistent activation of astroglial STAT3 following systemic LPS treatment (10 mg/kg) correlated with brain cell and microvasculature injury in the hippocampus, resulting in cognitive impairment." (PMID 28978145, 2017). "Recent data also suggest that inactivation of the JAK2/STAT3 signaling axis and M1 mAChR downregulation play a critical role in cognitive impairment observed in KLOTHO mutant mice." (PMID 25961830, 2015). "Experimental validation results demonstrated that PN improves depressive mood and cognitive impairment in SD mice by inhibiting the over-activation of the JAK1/STAT3 pathway, reducing oxidative stress and inflammatory responses, and modulating neurotransmitters." (PMID 40076470, 2025). "Previous studies have suggested that inhibition of STAT3 may ameliorate cognitive impairment in AD, suggesting that STAT3 could represent a novel therapeutic target." (PMID 39648181, 2024). "Previous studies have shown that enhancing CREB activity can improve cognitive deficits in animal models of neurodegenerative diseases, suggesting that STAT3 inhibitors might offer similar benefits." (PMID 39648181, 2024). "These genes are crucial for synaptic plasticity and long-term memory formation, suggesting that STAT3 inhibition may ameliorate cognitive impairments in neurodegenerative conditions." (PMID 39648181, 2024). "A recent study indicated that activated STAT3 signaling pathway may contribute to neuroinflammation and cognitive impairment in ligature-induced periodontitis rats." (PMID 37495990, 2023). "Based on these data, we speculated that the JAK2/STAT3 pathway is involved in regulating cognitive impairment induced by T2DM; it is unclear whether exercise plays a role in regulating the JAK2/STAT3 pathway." (PMID 35578689, 2022). "Our study showed that activation of the STAT3 by ligature-induced periodontitis could play an important role in the induction and amplification of neuroinflammation in cognitive impairment." (PMID 33757547, 2021).
Cognitive impairment (continued). "Here, by overexpressing human full length tau to mimic intraneuronal tau accumulation as seen in the sporadic AD cases, we investigated whether STAT3 is also involved in hTau-induced cognitive deficits." (PMID 33859760, 2021). "In addition, STAT3 was one of the key players in neuroinflammatory response that was found to be responsible for memory and cognitive impairment in certain extent." (PMID 33708168, 2021). "Here, we investigated the role of STAT3 in the cognitive deficits induced by hTau accumulation." (PMID 33859760, 2021). "Further research on the cognitive impairment of STAT3 should be verified in animal behavior assays." (PMID 34744770, 2021). "Overexpressing STAT3 attenuated the P301L-induced synaptic and cognitive deficits." (PMID 33361763, 2020). "We also found that STAT3 can directly bind the specific GAS element in GluN1, GluN2A, or GluN2B promoter and thus activate expression of NMDARs, which reveals a novel mechanism underlying Tau-induced synapse impairment of cognitive deficits." (PMID 33361763, 2020). "Thus, knockout of BDNF or TrkB in the hippocampus results in JAK2/STAT3, C/EBPβ, and δ-secretase upregulation and activation, resulting in increased neuroinflammation and neuronal cell death, leading to cognitive impairments." (PMID 31315045, 2019). "Therefore, in the present study, we explored the effect of aerobic exercise on cognitive impairment in T2DM mice and investigated whether the JAK2/STAT3 and AMPK/SIRT1 pathways are involved in the underlying mechanism." (PMID 35578689, 2022). "Therefore, study the role of STAT3 in the synaptic and cognitive deficits is an attractive idea." (PMID 33859760, 2021). "In this study, cognitive function was significantly impaired in the T2DM mice; aerobic exercise improved cognitive impairment through activating the AMPK/SIRT1 signalling pathway and inhibiting the JAK2/STAT3 signalling pathway in T2DM mice." (PMID 35578689, 2022). "The STAT3 signaling pathway was activated in this progress, which further resulted in abnormal APP processing and cognitive impairment." (PMID 33757547, 2021). "Stat3/VEGF signaling pathway is an important pathway that affects angiogenesis and cognitive deficits in the cerebral small vessel disease." (PMID 31434962, 2019). "For example, Dex has been reported to attenuate neuroinflammation and cognitive impairment by suppressing HMGB1/RAGE/NF-κB signaling and to reduce apoptosis and improve tissue survival after ischemia/reperfusion injury via activation of PI3K/Akt and STAT3." (PMID 41473658, 2025). "The SZRD, especially the L-SZRD, may improve the cognitive impairment and ameliorate the neural degeneration in APP/PS1 transgenic mice through inhibiting Aβ accumulation and neuroinflammation via the JAK2/STAT3 pathway." (PMID 33478552, 2021). "Treatment with EA may reduce the blood ammonia level, modulate inflammatory factors, ameliorate brain necrosis and apoptosis, and improve cognitive impairment through regulation of TLR4/MyD88/NF-κB and p38MAPK/STAT3 signaling pathways." (PMID 34630618, 2021). "Furthermore, treatment with SLT decreases LCN2 expression and the phosphorylation levels of Janus kinase-2 (JAK2) and signal transducer and activator of transcription-3 (STAT3) and mitigates the cognitive deficits in VaD rats." (PMID 33532143, 2021). "As STAT1 acetylation played a key role in the nuclear localization and transcriptional activity of STAT3, we infected AAV-STAT1KR (410/413R-STAT1) with AAV-P301L virus into C57 mice and investigated whether non-acetylated STAT1 overexpression attenuated P301L-induced synaptic and cognitive deficits." (PMID 33361763, 2020). "Further study found that overexpressing STAT3 or non-acetylated STAT1 (STAT1KR) ameliorated the hTau-induced synaptic plasticity impairment and cognitive deficits with upregulated NMDARs expression." (PMID 33859760, 2021).